IL17A (interleukin 17A)
Diseases named in the same sentence as IL17A in open-access papers (continued):
Sharing a sentence is not in itself a finding about the gene and the disease.
Obesity (320 papers, 2010 to 2026). Accumulation of substantial excess body fat. "This reduction in IL-17A corresponds to a decrease in adipocyte gene expression associated with obesity." (PMID 40636308, 2025). "In terms of cytokines, IL-17A, which is a strong activator of neutrophils, is significantly increased by obesity, and is associated with exacerbation of the pathophysiological factors of asthma in humans and mice." (PMID 40589493, 2025). "Overweight/obesity was also linked to increased plasma levels of IL-5, IL-17A, IL-22, IL-33, TNF-α, and leptin and decreased levels of IL-10." (PMID 39902293, 2024). "CCR6+ ILC3-derived IL-17A promotes the pathogenesis of obesity-associated airway hyperreactivity in Rag1−/− mice that are dependent on HFD-induced, macrophage-derived IL-1β." (PMID 39872860, 2023). "High levels of Deferribacteres are often related to obesity, which is positively linked with the pro-inflammatory factors, IL-6, IL-17A, and TNF-α, causing the aggravation of inflammation in obesity." (PMID 37376017, 2023). "The production of IL-17A is enhanced by ATDCs in both mice and humans, which has clear clinical implications in obesity-associated metabolic disorders." (PMID 36781473, 2023). "Having demonstrated that LKB1 loss in DCs exacerbates obesity-induced metabolic dysfunctions in an IL-17A–dependent fashion, we next investigated the signaling mediators downstream of LKB1 involved in the Th17 priming function of DCs." (PMID 37140993, 2023). "Further, reduced obesity and improved metabolic markers are observed by IL-17RA deletion from adipocytes, where IL-17A phosphorylation of PPARγ is associated with the repression of browning and expression of diabetogenic and obese genes." (PMID 36140808, 2022). "It has been reported by earlier studies that IL-17 related chemokine (Eotaxin) is central to the amount of visceral fat and obesity was associated with increased IL-17A production in humans." (PMID 35578222, 2022). "IL-17A has been implicated in obesity in recent years, with obese women exhibiting elevated levels of IL-17 compared to their non-obese counterparts; therefore, it is unsurprising that levels are higher in the secretome of VAT compared to SAT." (PMID 34822426, 2021). "It has also been reported that γδT cells secreted IL-17A, obesity induced GM-CSF and IL-5, periostin and Elf5 are associated with neutrophils recruitment in the lung." (PMID 33178575, 2020). "In this review, we will highlight the pathogenic role of IL-17A producing cells in the mechanisms leading to inflammation in obesity and to progression of obesity-related inflammatory diseases." (PMID 28708082, 2017). "Recent studies showed the potential implication of IL-17A in human obesity-linked inflammation and co-morbidities." (PMID 26263971, 2015). "The purpose of this study was to examine the temporal association between the onset of AHR and changes in IL-17A during the development of obesity by high-fat feeding in mice." (PMID 25309539, 2014). "Although a Th17 pro-inflammatory bias has been clearly linked with obesity, there’s evidence of a dichotomy in effects of IL-17A in adipogenesis." (PMID 23874682, 2013). "For example, IL-17A has been associated and studied for its contribution to obesity." (PMID 36140808, 2022). "Furthermore, IL17A is increasingly showing a direct pathogenic role in obesity, diabetes, and hypertension." (PMID 35572968, 2022). "ILC3 produced IL-17A and caused obesity-related AHR effects." (PMID 35656293, 2022). "However, animal studies have shown that an IL-17A deficiency increases diet-induced obesity in mice and prevents the development of disorders related to glucose metabolism." (PMID 34322117, 2021). "Regarding obesity grade, although it is not possible to determine the causality of the fact that the levels of IL-17A were decreased in serum of obese patients, the reported results suggest that in this type of extreme obesity, adipose tissue behaves in a differential way than expected." (PMID 26263971, 2015).
Obesity (continued). "Among others, obesity, is associated with increased IL-17A production in humans." (PMID 25092442, 2014). "Interestingly, obesity, especially long-chain FFAs, causes Treg loss in the skin and simultaneously increases IL-17A+ γδ T cells by reducing PPARγ+ skin Treg cells and a corresponding loss of control over IL-17A+ γδ T cell-mediated inflammation." (PMID 38642273, 2024). "Additionally, the differences in metabolic gene expression as well as signaling pathway activation in obese mouse adipose tissue versus lean mouse adipose tissue reveal that IL-17A in obese mice induces expression of genes associated with diet-induced obesity (DIO) and dampen glucose transport." (PMID 36140808, 2022). "B. pseudocatenulatum CECT 7765 reduced obesity-associated systemic inflammation by restoring the balance between regulatory T cells (Tregs) and B lymphocytes and reducing pro-inflammatory cytokines of adaptive (IL-17A) and innate (TNF-α) immunity and endotoxemia." (PMID 26161548, 2015). "Further, the beneficial roles of IL-17A in the context of obesity are balanced with the presence of other inflammatory cytokines." (PMID 40529363, 2025). "Obesity and metabolic syndrome are known to interact with the immune system, stimulating the production of pro-inflammatory cytokines, including TNFα and IL17A, with a potential synergistic role in promoting oxidative damage and telomere instability." (PMID 41249702, 2025). "Research indicates that increased activation of the interleukin IL‐17 axis regulates liver damage, and neutralizing IL‐17A alleviates obesity‐driven hepatocellular damage in mice." (PMID 40900445, 2025). "Studies have shown that obesity can recruit inflammatory factors such as IL‐17A and IL‐10,11, 12, 13 and promote the production of MDSCs." (PMID 38501542, 2024). "Based upon the cytokine production patterns of splenic T helper cells upon stimulation with PMA, obesity seems to enhance the capacity of these cells to produce IL-10, while it diminished IL-17A production." (PMID 39201761, 2024). "IL-17A neutralization prevents exacerbated obesity-induced metabolic dysfunctions in CD11cΔLKB1 mice." (PMID 37140993, 2023). "In summary, these findings reveal that Lkb1 is essential for fat CD11c+ dendritic cells responding to HFD exposure and provides new insights into the IL-17A/IFN-γ balance in HFD-induced obesity." (PMID 36781473, 2023). "This suggests a link between the cellular lipid metabolic programme key to IL-17A-producing aaMAIT cells discovered here, and human organ/organism-level diseases related to lipid dysbiosis, including metabolic syndrome and obesity." (PMID 37231163, 2023). "Obesity-induced hepatic Th17 cells and IL-17A signaling have consistently been reported to impair insulin sensitivity and promote hepatic steatosis and fibrosis in both HFD-fed mice and patients with NAFLD/NASH." (PMID 37140993, 2023). "IL-17A is an important regulator of glucose homeostasis, adipogenesis, and obesity that also plays a critical role in the crosstalk between obesity and Th17-associated immune response in AT." (PMID 35456006, 2022). "Consistent with the heightened activation of PRRs, ELISA showed that serum cytokine concentrations of TNF-α, IFN-γ, IL-1β, IL-6, and IL-17A were significantly induced with obesity, as was anti-inflammatory TGF-β and IL-10." (PMID 36406423, 2022). "In connection with this, it has been reported that IL17A negatively regulates adipogenesis and glucose metabolism in mice and delays obesity development." (PMID 35282365, 2022). "Because we were focusing on inflammatory cytokines that play a major role in developing obesity, we quantified the level of IL-1β, IL-6, IL-17A, IFN-γ and TNF-α in the plasma of lean, HFD and GaELNs treated HFD mice." (PMID 35154484, 2022).
Obesity (continued). "This intestinal-specific IL-17–microbiota–metabolism axis is of special interest because it differs from the traditional view of obesity as a proinflammatory state, where researchers found increased levels of IL-17A in the serum and visceral adipose tissues." (PMID 36140808, 2022). "IL-17A is also referred to as IL-17 and has so far been the most studied interleukin in this group in correlation with obesity and the metabolic syndrome." (PMID 35277002, 2022). "In this study, we show that obesity is associated with increased CD4+ T cell proliferation and IL-17A production in PLWH." (PMID 35111163, 2021). "IL-17A and Th17 cells have been previously identified as pivotal components in the induction of autoimmune type I diabetes, initiation of obesity-driven type II diabetes and insulin resistance, and the onset of multiple diabetic complications." (PMID 33919327, 2021). "Though literature for IL-17A’s role in the formation of the fatty tissues is sparse, our findings are similar to those seen in investigations on obesity and the potential role of IL-17A in the development of insulin resistance." (PMID 33562025, 2021). "Obesity and HIV infection are associated with increased secretion of pro-inflammatory cytokines, including IL-17A, and higher IL-17A serum levels and increased Th17 cells." (PMID 35111163, 2021). "In fact, abolishing the IL-17A axis in preclinical models has been proven to suppress diet-induced obesity by promoting adipose-tissue browning, thermogenesis and energy expenditure." (PMID 34899679, 2021). "The enrichment of the Deferribacteres and Tenericutes population is a common phenomenon in obesity, which is positively linked with the pro-inflammatory factors IL-6, TNF-α, and IL-17A, causing aggravation of inflammation in obesity." (PMID 33585429, 2021). "Further research should be conducted to evaluate the effects of IL-17A inhibition in depressed patients, taking into account other common comorbidities, such as metabolic syndrome and obesity." (PMID 33322667, 2020). "Obesity and non-alcoholic fatty liver disease (NAFLD) have been associated with an increase in IL-17A, which is produced in the intestinal mucosa, and its levels are modulated by microbiome composition." (PMID 32498372, 2020). "Very little amount of literature is available on the role of IL-17F in obesity as it is simply described as a closely related cytokine of IL-17A." (PMID 32849611, 2020). "IL-17A alone was used due to the overwhelming amount of literature that suggests a role for this proinflammatory cytokine in obesity." (PMID 32849611, 2020). "In MGAT of HFD-fed mice, we found 3.4X IL-17A-expressing CD4+ T cells compared to MGAT of ND-fed mice, paralleling what is observed in the subcutaneous adipose tissue of patients with obesity-associated T2D." (PMID 31015794, 2019). "While IL-17RA, in part via IL-17A, was previously determined to regulate obesity-dependent NAFLD, our novel data show that hepatic IL-17RA expression is actually increased during MCDD-induced NAFLD." (PMID 26895034, 2016). "The findings demonstrate that a transient early postnatal overweight induces early-onset (P21) obesity, accompanied by activation of pulmonary adipocytokine/insulin signaling and increased pulmonary expression of pro-asthmatic IL-6, IL-13, IL-17A and Tnf-α." (PMID 27087690, 2016). "The most significant alterations of immune markers associated with HFD-induced obesity in serum were those of TNF-α, IL-18 and IL-17A, whose concentrations significantly increased (p<0.001–0.013)." (PMID 26161548, 2015). "It has been widely shown that IL-6 expands the TH17 fraction in obesity while being concurrently induced by IL-17A itself." (PMID 26263971, 2015). "Data from recent studies conducted in rodent models and humans suggest that interleukin-17A (IL-17A) plays a role in the induction of inflammation in adipose tissue during obesity." (PMID 26263971, 2015).
Obesity (continued). "Obesity is also positively correlated with increased IL-17A expression and increased severity of inflammation in IL-17A-dependent mouse models." (PMID 26263971, 2015). "Some recent studies have shown that obesity is directly related to IL-17A expression and increased severity of inflammation in IL-17A-dependent mouse models." (PMID 26263971, 2015). "It has recently been suggested that IL-17A plays a role in the induction of inflammation in adipose tissue during obesity, glucose homeostasis and adipogenesis." (PMID 26263971, 2015). "Mice deficient in IL-17A do not develop AHR with high-fat feeding, suggesting an important role for IL-17A in the development of the innate AHR of obesity." (PMID 25309539, 2014). "In our previous studies we found that dietary probiotics counteract obesity and age-related integumentary pathology at least in part by down-regulating systemic pro-inflammatory IL-17A-dependent signaling." (PMID 24392159, 2014). "Taken together, the data suggest that obesity-related reductions in neutrophil recruitment induced by subacute O3 exposure are the result of reduced IL-17A-dependent G-CSF release, consequent to reduced IL-6 and IL-23 expression." (PMID 24823369, 2014). "IL-17A is a well-known inflammatory cytokine in the context of obesity." (PMID 40529363, 2025). "The presence of IL-17A turned out to be necessary for obesity-induced AHR, as it was not seen in the IL-17A-deficient animals." (PMID 38542187, 2024). "Regarding the metabolic effects, disrupting the IL-17 pathway through genetic deletion (Il17a-/-) or blocking its signaling (Il17ra-/-) resulted in increased weight gain and adiposity in models of diet-induced obesity and MASLD." (PMID 39156888, 2024). "Furthermore, it explores the role of pro-inflammatory cytokines, such as IL-6 and IL-17a and mother’s obesity as potentially environmental factors of ASD." (PMID 38398873, 2024). "In children with overweight/obesity, the levels of pro-inflammatory cytokines, particularly IL-5, IL-17A, IL-33, TNF-α, and leptin, were also elevated, which is consistent with previous findings, indicating chronic low-grade inflammation associated with obesity." (PMID 39902293, 2024). "Emerging evidence suggests that ILC3s may regulate obesity or metabolic homeostasis through the secretion of IL-17A or IL-22." (PMID 39872860, 2023). "Pharmacological blockade of mitoSTAT3 either by a mitochondria-targeted STAT3 inhibitor or ROS scavenging prevented obesity and fatty acid–induced production of proinflammatory cytokines IL-17A and IL-6, thus establishing a mechanistic link between mitoSTAT3 and inflammatory cytokine production." (PMID 35928250, 2022). "Mechanistically, IL-17A induces phosphorylation of the serine 273 site of PPARγ in adipocytes in a Cyclin-dependent Kinase 5 (CDK5)-dependent manner, which subsequently modifies the expression of obesity-associated genes." (PMID 35574038, 2022). "IL-17A production exacerbated obesity-induced hepatocellular damage." (PMID 34211477, 2021). "In a mouse model of diet-induced obesity, IL-17A production was enhanced by CD4+ T cells." (PMID 32849611, 2020). "IL-17A-deficient mice with HFD developed obesity to the similar extent to that of HFD-fed wild-type (WT) mice, and the increase of dermal γδ T cells was observed in both WT and IL-17A-deficient mice." (PMID 29074858, 2017). "Notably, IL-17RA signaling, via IL-17A, plays an important role in obesity-driven NAFLD pathogenesis." (PMID 26895034, 2016). "In conclusion, it has been previously established that IL-17A is required for obesity-related AHR." (PMID 25309539, 2014). "IL-17A has been linked to the development of innate AHR in obese mice: compared to chow, HFD feeding results in both obesity and AHR in WT mice, whereas AHR is not observed in mice deficient in IL-17A despite equal induction of obesity." (PMID 25309539, 2014).
Obesity (continued). "Our data suggest that obesity-related reductions in pulmonary Cfd expression may contribute to effects of IL-17A that promote obesity-related AHR." (PMID 25309539, 2014). "Finally, our data indicate that obesity-related reductions in the ability of subacute O3 to promote neutrophil recruitment to the lungs are the result of reduced IL-17A+ γδ T cells." (PMID 24823369, 2014). "Nonetheless, these mice exhibited elevated levels of Il-17A, whether a result of the diet, or microbes, or from the obesity itself." (PMID 23874682, 2013). "Obesity is accompanied by chronic inflammation associated with hypoxia and adipocyte dysfunction, which resultsinappearance of pro-inflammatory cytokines such as TNF-alpha, IL-6, MCP-1, IL-1 beta and IL-17A, likely to play a role in lung injury associated with ARDS." (PMID 34960696, 2021). "In patients with obesity, adipose tissue-associated and circulating T cells are preferentially skewed towards inflammatory Th1- and/or Th17-type T cells and studies have shown that IFN-γ and IL-17A contribute to aberrant glucose and lipid homeostasis in several cell types, including adipocytes." (PMID 31015794, 2019). "Given that: (a) IL-17A has a causal role in multiple models of liver injury; (b) IL-17F shares a receptor with IL-17A; and (c) IL-17RA mice are protected from obesity-induced NASH, we hypothesized that both IL-17A and IL-17F signaling through IL-17RA is critical to NAFLD progression." (PMID 26895034, 2016). "Further, the observations that increases in pulmonary Il17a mRNA expression preceded, whereas the onset of the systemic inflammation of obesity coincided temporally with the development of AHR suggest that systemic inflammation may interact with IL-17A to promote AHR." (PMID 25309539, 2014). "Lastly, we wanted to see if the treatment class, disease duration, obesity, alcohol consumption, smoking habit, or gender has an effect on serum levels of TNF-α, IL-17A, IL-17F, and IL-12/23 at the onset of treatment or after 12 weeks." (PMID 40699767, 2025). "The inflammatory state is not limited to the local fat, but cytokines also enter the bloodstream and a range of pro-inflammatory cytokines, including IL1B, IL17A, IL-2, IFNalpha, gamma and TNF are increased in peripheral blood of individuals with obesity." (PMID 41227037, 2025). "Obesity increased splenic Th1 and regulatory T cells, MLN Th1 and PP Th17 cells and enhanced IFN-γ and IL-17A production by splenic Th cells upon ex vivo stimulation." (PMID 39072322, 2024). "An increase in circulating levels of cytokines (IL-1β, IL-6, and IL-17A) and their production under the influence of the HFCD diet is also specific for the development of diet-induced obesity and metabolic syndrome." (PMID 33670919, 2021). "In similar studies, exposure to high fat diet during lactation (only) induced an early-onset obesity in offspring (C57BL/N mice) at 3 weeks of age, with increased expression of mRNAs of IL-5, IL-13, IL-17A and TNFα in the lung." (PMID 30700289, 2019). "In a mouse model of obesity, mice fed with a high-fat diet had significantly elevated numbers of ILC3-producing IL-17A in their lungs and developed AHR spontaneously." (PMID 30622974, 2018). "IL-17A can induce expression of TNF-α, IL-6, and IL-1β cytokines, which are found with increased levels in obesity." (PMID 27070576, 2016). "In conclusion, IL-17A expression in VAT is increased in morbidly obese women, which suggests a link between obesity and innate immunity in low-grade chronic inflammation in morbidly obese women." (PMID 26263971, 2015). "Statistically, the concentrations of GROα, IL-2, IL-4, IL-6, IL-17A, IL-22, IL-23, and MCP-3 were significantly higher in males with obesity compared to the females with obesity, while the concentrations of IL-5, IL-10, IL-18, MCP-1, and MIP2α trended higher (p ≤ 0.1)." (PMID 41488663, 2025).